BRCA1 (BRCA1 DNA repair associated)
Diseases named in the same sentence as BRCA1 in open-access papers (continued):
Sharing a sentence is not in itself a finding about the gene and the disease.
pancreatic cancer (continued). "Hereditary breast and ovarian cancer (HBOC) syndrome is primarily associated with mutations in BRCA1 and BRCA2, but increasing evidence links it to other malignancies, including male breast, prostate, and pancreatic cancers." (PMID 40649708, 2025). "The most common mutations were found in the BRCA1, BRCA2, ATM, PALB2, and CDKN2A genes, further highlighting the involvement of DDR-related genes in pancreatic cancer." (PMID 41155399, 2025). "Individuals with PGVs in BRCA1 or BRCA2 have a well-established increased risk of breast, ovarian, prostate, and pancreatic cancers." (PMID 39932614, 2025). "Pathogenic variants in the BRCA1 and BRCA2 genes increase the relative and absolute risks of developing breast, ovarian, prostate, and pancreatic cancer." (PMID 40772289, 2025). "Given the existence of targeted agents (PARP inhibitors) that are approved for BRCA1/2 mutant patients in several cancers, including breast, ovarian, prostate, and pancreatic cancer, it would be interesting to delineate these genes’ role in USCs." (PMID 40422510, 2025). "We identify OFD1 as a positive regulator of BRCA1 in human pancreatic cancer cells and specimens, with its overexpression correlating with poor prognosis." (PMID 40764600, 2025). "Because of this, BRCA1 and BRCA2 carriers have a well-established increased risk of multiple cancers, most notably, breast, ovarian, prostate and pancreatic cancers." (PMID 41256354, 2025). "In this study, we identify a strong positive correlation between OFD1 and BRCA1 expression in pancreatic cancer." (PMID 40764600, 2025). "The PDAC cohorts were classified into strong, moderate and weak expression groups based on their IHC intensity and area, OFD1 and BRCA1 expression showed a strong correlation in these pancreatic cancer samples." (PMID 40764600, 2025). "Germline pathogenic or likely pathogenic variants (PVs) in the BRCA1 and BRCA2 (BRCA) genes increase the relative and absolute risks of breast, ovarian, and other cancers, such as prostate and pancreatic cancer." (PMID 40772289, 2025). "The cumulative risks to those at age 80 are reported as being approximately 2.5% for pancreatic cancer for both BRCA1 and BRCA2 carriers, and 27% for prostate cancer for BRCA2 carriers." (PMID 39996890, 2025). "Germline mutations in BRCA1 and BRCA2 markedly increase the risk of several solid malignancies, most notably breast, ovarian, and pancreatic cancers." (PMID 41457124, 2025). "Pancreatic cancer showed an exceptionally high biallelic loss in HRR genes, with BRCA1, CDK12, FANCC, PPP2R2 A, RAD51 C, RAD51D, RAD52, WRN, and XRCC3 all presenting 100% biallelic loss." (PMID 40420266, 2025). "PARP inhibitors are currently FDA-approved for BRCA1- and BRCA2-mutated breast, ovarian, prostatic, and pancreatic tumors." (PMID 40842586, 2025). "Of the 6474 patients with pancreatic cancer, 27 (0.4%) had BRCA1 alterations, 108 (1.7%) had BRCA2 alterations, 76 (1.2%) had germline ATM alterations, 25 (0.4%) had PALB2 alterations, and 27 (0.4%) had CHEK2 alterations." (PMID 40361359, 2025). "In recent years, multiple reports have shown that BRCA1, BRCA2 and PALB2 genes, which are known as “the core homologous recombination (HR) genes”, present germline mutations in up to 5% of patients with pancreatic cancer." (PMID 40124650, 2025). "BRCA1 and BRCA2 carriers have a well-established risk of multiple cancers including breast, ovarian, prostate and pancreatic cancers." (PMID 41256354, 2025). "Currently, germline panels for PALB2 and BRCA1/2 are utilized for breast, ovarian, and pancreatic cancer." (PMID 40948682, 2025). "Regarding pancreatic cancer, Olaparib is the only PARP inhibitor that has been FDA-approved for usage in patients with pancreatic cancers with BRCA1 or BRCA2 mutations." (PMID 40842586, 2025).
pancreatic cancer (continued). "In the present study, we established a BRCA1 knockout (KO) pancreatic cancer cells and subsequently isolated an olaparib-resistant clone from these cells." (PMID 38625917, 2024). "We examined the methylation status of BRCA1 in cell-free DNA from 55 operable pancreatic cancer patients." (PMID 38577595, 2024). "To investigate mechanisms of PARP inhibitor resistance, we established a BRCA1 knockout clone derived from the pancreatic cancer MIA PaCa-2 cells, which we termed C1 cells, and subsequently isolated an olaparib-resistant C1/OLA cells." (PMID 38625917, 2024). "Deleterious BRCA1/2 (BRCA) mutation raises the risk for BRCA mutation-related malignancies, including breast, ovarian, prostate, and pancreatic cancer." (PMID 38566028, 2024). "The reported pancreatic cancer risks in BRCA1 and BRCA2 carriers by the age of 70 years were 1.16% and 4.1% in men." (PMID 38929805, 2024). "Patients with operable pancreatic cancer and a methylated BRCA1 and BRCA2 promoter status had a statistically significant poorer outcome as compared with patients with a non-methylated one (p=0.012 and p=0.001, respectively)." (PMID 38577595, 2024). "Maintenance rucaparib has proven to be a safe and effective maintenance option for PALB2 PV/LPV patients, in addition to BRCA1/2, with platinum-sensitive advanced pancreatic cancer in a phase 2 trial, and it is a current FDA approved-indication." (PMID 39796639, 2024). "Only 29% (22/79) of websites (38%, 17/45 UKOs; 13%, 2/16 JCOs; 17%, 3/18 GTPs) provided information about BRCA1/BRCA2-associated male BC, prostate, pancreatic cancers, and/or melanoma risks." (PMID 39001386, 2024). "We examined the methylation status of BRCA1 in cell-free DNA from 50 metastatic pancreatic cancer patients." (PMID 38577595, 2024). "PARP inhibitors are effective in treating patients with ovarian, breast, prostate, or pancreatic cancers who had HRD and/or BRCA1/2 mutations with PVs." (PMID 39590127, 2024). "The development of pancreatic cancer is significantly associated with mutations in key DDR genes, such as BRCA-1 and BRCA-2." (PMID 39001391, 2024). "Targeted treatments in pancreatic cancer, such as PARP inhibitors, are limited to a small subset of patients with BRCA1/BRCA2 mutations." (PMID 38607041, 2024). "PARP inhibitor therapy is approved for HGSOC, prostate and pancreatic cancer based on alterations of BRCA1/2 genes or HRD index." (PMID 38881341, 2024). "We explored various combinations of HDACi and PARPi +/− decitabine (hypomethylating agent) in pancreatic cancer cell lines BxPC-3 and PL45 (wild-type BRCA1 and BRCA2) and Capan-1 (mutated BRCA2)." (PMID 38829622, 2024). "Within familial pancreatic cancer, defined by the presence of two or more first-degree relatives affected with pancreatic cancer, BRCA2 mutations are discerned in about 5% to 10% of cases, and BRCA1 mutations are found in approximately 1%." (PMID 38809921, 2024). "Among Ashkenazi Jewish breast cancer patients, a higher BRCA1 and BRCA2 mutation rate was found to be associated with a family history of pancreatic cancer." (PMID 39595558, 2024). "In this study, we attempted tο detect and observe the methylation status of BRCA1/2 genes in the cell-free DNA of a small cohort of pancreatic cancer patients." (PMID 38577595, 2024). "Pathogenic BRCA1 or BRCA2 germline mutations contribute to hereditary breast, ovarian, prostate, and pancreatic cancer." (PMID 39198848, 2024). "Mutations in genes such as BRCA1, BRCA2, PALB2, and ATM are associated with an increased risk of pancreatic cancer, particularly in individuals with a family history of the disease." (PMID 39409171, 2024).
pancreatic cancer (continued). "Mutations in the BRCA1 and BRCA2 genes are well-known risk factors for breast and ovarian cancer, but they also increase the risk of pancreatic cancer." (PMID 39409171, 2024). "The combination of KLF5 inhibitors and PARP inhibitors provides a novel treatment strategy to enhance the sensitivity of BRCA1-proficient pancreatic cancer to PARP inhibitors." (PMID 38433576, 2024). "Nevertheless, the role of epigenetic silencing of BRCA1/2 in pancreatic cancer remains controversial." (PMID 38577595, 2024). "To analyze the mechanism of olaparib resistance in pancreatic cancer cells with BRCA1 dysfunction, we first isolated four BRCA1 KO candidate clones obtained using the CRISPR/Cas9 system." (PMID 38625917, 2024). "Poly(ADP-ribose) polymerase (PARP) inhibitors have been recently approved for BRCA1/2-mutant pancreatic cancer, opening a new era for targeted therapy for this disease." (PMID 37415733, 2023). "It is well known that carrying deleterious germline mutations in the BRCA1 and BRCA2 genes can increase the risk of developing pancreatic cancer." (PMID 37232812, 2023). "Our findings emphasize the need for a better understanding of possible biological differences between pancreatic cancers that develop in patients with BRCA1 PVs vs BRCA2 PVs and consideration of stratification by mutation type in future clinical trials." (PMID 38010655, 2023). "Germline BRCA1 and BRCA2 mutations (gBRCAm) can inform pancreatic cancer (PC) risk and treatment but most of the available information is derived from white patients." (PMID 36822114, 2023). "In total, 63 different heterozygous variants were identified in BRCA1 (n = 27) and BRCA2 (n = 36) among unselected Pakistani pancreatic cancer patients." (PMID 37951914, 2023). "The significance of BRCA1/2 genetic testing in pancreatic cancer patients is recently recognized among Caucasians, however, limited reports are available among Asians." (PMID 37951914, 2023). "As discussed in a previous section, besides BRCA1 and BRCA2 mutations, mutations in PALB2, ATM, ATR, BRIP1, BARD1 and CDK12 are observed in low frequencies in pancreatic cancers." (PMID 36975505, 2023). "BRCA1 and BRCA2 (BRCA1/2) are the most frequently investigated genes among Caucasian pancreatic cancer patients, whereas limited reports are available among Asians." (PMID 37951914, 2023). "The mutation rates of BRCA1 and BRCA2 in familial pancreatic cancers are <1.2% and 5–17%, respectively, and those mutations increase the risk of disease by 2.26-fold and 3.5 to 10-fold." (PMID 37304241, 2023). "Of these genes, BRCA1 and BRCA2 (BRCA1/2) are the most frequently investigated to assess their contribution to pancreatic cancer risk among Caucasians." (PMID 37951914, 2023). "An improvement in the approach to pancreatic cancer is targeted therapies for the individualisation of treatment (BRCA1/2 or BRCA1)." (PMID 37174011, 2023). "A neo-adjuvant chemotherapy study in patients with germline BRCA1/BRCA2 mutations and borderline resectable pancreatic cancer showed a complete pathologic response rate of 44.4%." (PMID 36975505, 2023). "In a large cohort of patients with germline BRCA PVs and pancreatic cancer, BRCA2 PVs were associated with better outcomes compared with BRCA1 PVs." (PMID 38010655, 2023). "Considering the relationship between aging, invasion, and metastasis of pancreatic cancer, it is crucial to consider ITGA2 mutation as significant as CDKN2A, BRCA1/2, and PALB2 mutations in the diagnosis and treatment of pancreatic cancer." (PMID 37881431, 2023). "The expression of BRCA1 mRNA in tumor tissues of 25 patients with pancreatic cancer was detected in this retrospective study." (PMID 36387089, 2022).
pancreatic cancer (continued). "While both BRCA1 and BRCA2 mutations have been extensively studied relative to pancreatic cancer risk, these screening studies have also demonstrated a higher prevalence of IPMNs in patients with BRCA mutations." (PMID 35884779, 2022). "Third, only two patients underwent germline genetic testing following the result of tumor sequencing because germline pathogenic BRCA1 and/or BRCA2 mutations are the only approved indication for targeted therapy in pancreatic cancer." (PMID 36463295, 2022). "Multigene germline panel testing is recommended for Pancreatic Cancer (PC) patients; however, for non-BRCA1/2 genes, the clinical utility is unclear." (PMID 36139606, 2022). "Poly (ADP-ribose) polymerase (PARP) inhibitors have been approved in malignancies associated with germline BRCA1 or BRCA2 pathogenic variants, such as breast, ovarian, prostate, and pancreatic cancer." (PMID 36577523, 2022). "BRCA1/2 and PALB2 pathogenetic carriers in heterozygosis have also higher relative risk for pancreatic cancer." (PMID 35454911, 2022). "Previous trials have shown the positive effects of PARP inhibitors in breast and ovarian cancer patients involving BRCA1 or BRCA2 mutations, with similar findings in pancreatic cancer patients." (PMID 36291766, 2022). "We aimed to evaluate the efficacy and safety of individualized chemotherapy combined with sequential immunotherapy based on BRCA1 mRNA expression in unresectable pancreatic cancer." (PMID 36387089, 2022). "Which cancer types and their clinical characteristics are associated with pathogenic variants in BRCA1 and BRCA2 in addition to breast, ovarian, prostate, and pancreatic cancers?" (PMID 35420638, 2022). "For example, pathogenic BRCA1, BRCA2 and PALB2 variants are associated with both male BC and pancreatic cancer." (PMID 36115878, 2022). "Mutations in BRCA1 and BRCA2 genes are often found in breast cancer patients, and approximately 5% of pancreatic cancer patients also have mutations in these genes." (PMID 36291766, 2022). "The implementation of this recommendation is hampered by the uncertainty around the clinical utility of multigene testing in pancreatic cancer patients, particularly for genes other than BRCA1/2." (PMID 36139606, 2022). "Overall, BRCA1/2 PVs can be found in both germline and somatic samples from pancreatic cancer patients at similar rates." (PMID 35563100, 2022). "Pathogenic mutations in BRCA1 and BRCA2 are associated with an increased risk of developing breast, prostate, and pancreatic cancer, as well as other cancers, among men and women." (PMID 35303741, 2022). "The aim of our study was to investigate the effect of individualized chemotherapy combined with sequential immunotherapy based on BRCA1 mRNA expression on the objective efficacy and survival conditions of patients with unresectable pancreatic cancer." (PMID 36387089, 2022). "The IC50 of Olaparib on BRCA1/2-proficient human pancreatic cancer MIA PaCa-2 and PANC-1 cell lines was 200 μM, while the IC50 of Niraparib was 26 μM and 50 μM, respectively." (PMID 36324587, 2022). "Olaparib and rucaparib were tested in phase II trials including approximately 20 germline BRCA1/2 mutant pancreatic cancer patients." (PMID 35163129, 2022). "We believe that if a BRCA1/2 PV carrier is already undergoing an EUS for pancreatic cancer surveillance, a standard upper endoscopy should also be performed concurrently with careful inspection for upper GI neoplasia." (PMID 36497436, 2022).
pancreatic cancer (continued). "Hereditary breast–ovarian cancer syndrome, attributed to BRCA1 or BRCA2 mutations, is also associated with increased risk of developing pancreatic cancer." (PMID 36500723, 2022). "The BRCA1 gene expression level is expected to be a biomarker for the decision-making of chemotherapy regimen in patients with unresectable pancreatic cancer." (PMID 36387089, 2022). "In 6,902 men with BRCA1 or BRCA2 mutations who developed cancer, especially breast, prostate, and pancreatic cancer, and multiple primary tumors, there was an association with a higher rate of BRCA2 mutations." (PMID 35251954, 2022). "Approximately 0.7%–5.7% and 0.3%–2.3% of unselected cases of pancreatic adenocarcinoma are linked to pathogenic mutations, respectively, in BRCA1 and BRCA2 genes, making them the most common cause of familial pancreatic cancer." (PMID 36307994, 2022). "Germline mutations associated with pancreatic cancer are ATM (2%–4%), BRCA1 (0%–1%), BRCA2 (8%–19%), CHEK2 (2%–9%), and PALB2 (3.1%–3.7%)." (PMID 33764904, 2021). "retrospectively analyzed clinical data of 71 patients with BRCA1/2-mut pancreatic cancer and observed a significantly longer OS for individuals with an advanced disease when treated with a platinum therapy compared with nonplatinum treatment (22 vs. 9 months)." (PMID 34707985, 2021). "In our study, there were 4 cases of pancreatic cancers among 20 BRCA1 and BRCA2 carriers, 2.5 times the frequency in the group with no pathogenic variants identified." (PMID 35155181, 2021). "Among unselected pancreatic cancer patient cohorts, multiple studies have shown to estimate the incidence of germline BRCA mutations ranged from 0.7–5.7% for BRCA2 and 0.3–2.3% for BRCA1." (PMID 34356066, 2021). "Few data are available about BRCA1/2 testing on pancreatic tumor tissues, which often include limited biological material." (PMID 34200245, 2021). "Germline mutations in the tumor suppressors BRCA1, BRCA2, or both genes are linked to an increased risk of developing pancreatic cancers." (PMID 33959007, 2021). "BRCA1/2 testing on pancreatic tumor tissues can also be feasible on small biopsies, but more cases must be analyzed to define its role and value in the PDAC diagnostic algorithm." (PMID 34200245, 2021). "BRCA1/2 germline mutations were not only reported in HBOC, but also reported in many other cancer types, including pancreatic cancer, lung cancer, urothelial carcinoma and esophageal cancer." (PMID 33563323, 2021). "In conclusion, only few data are available about BRCA1/2 molecular testing on clinical FFPE specimens from pancreatic tumors." (PMID 34200245, 2021). "In the phase II RUCAPANC trial enrolling 19 BRCA1/2-mut pancreatic cancer patients (with three of those harboring a somatic BRCA mutation), rucaparib led to response in 15.8% (n = 3, 2 PR, 1 CR) of patients." (PMID 34707985, 2021). "The biological impact of BRCA1 and BRCA2 mutations are histology-dependent, in that they are indispensable founding events in some tumors (e.g., breast, ovarian, prostate and pancreatic cancer) and inert in others." (PMID 34572943, 2021). "Several studies reported that BRCA2 carriers had higher relative and cumulative risks of pancreatic cancer compared to BRCA1 carriers." (PMID 34356066, 2021). "A prospective study of 5,149 females with BRCA1 or BRCA2 carriers showed a significant 2.4-fold increase in the incidence of pancreatic cancer and the increase in the incidence of pancreatic cancer was similar for BRCA1 (SIR = 2.55) and BRCA2 (SIR = 2.13)." (PMID 34356066, 2021). "Olaparib is also recommended as a maintenance treatment for hereditary BRCA1/2-driven pancreatic cancer." (PMID 34454564, 2021).